SIRT3 (sirtuin 3)
Diseases named in the same sentence as SIRT3 in open-access papers (continued):
Sharing a sentence is not in itself a finding about the gene and the disease.
Insulin resistance (continued). "Interestingly, α-Man increases SIRT3 expression level, which might mediates the protective role of α-Man against aging-associated insulin resistance, hyperlipidemia and liver injury." (PMID 31806859, 2019). "Researchers have found that SIRT3 activation enhances insulin sensitivity through the regulation of insulin signaling, whereas SIRT3 inhibition exacerbates insulin resistance." (PMID 40799515, 2025). "Improves glucose tolerance, reduces hyperglycemia, enhances IL-22 production, restores intestinal barrier integrity, promotes mitochondrial function via SIRT3, and reduces insulin resistance in HFD mice." (PMID 39963239, 2025). "The results showed that both global and BAT regional endothelium-specific Sirt3 knockout accelerated diet-induced weight gain, accompanied by glucose intolerance, insulin resistance, and BAT whitening." (PMID 40520025, 2025). "SIRT3 knockout mice develop insulin resistance due to the hyperacetylation of mitochondrial proteins in skeletal muscles." (PMID 41304967, 2025). "In contrast, a high-fat diet (HFD) has the opposite effect, reducing SIRT3 expression and leading to metabolic disorders like obesity and insulin resistance." (PMID 40799515, 2025). "Calculation of the Homeostasis model assessment of basal insulin resistance (HOMA-IR) values suggested that AT-specific SIRT3 overexpression improved insulin sensitivity in HFD-feeding." (PMID 40368890, 2025). "SIRT3 expression reduction contributes to insulin resistance, and its overexpression enhances glucose uptake and reduces ROS production in insulin-resistant muscle cells 29,141,142." (PMID 38904020, 2024). "Animal studies have demonstrated that mice fed with high-fat diet exhibit reduced SIRT3 activity, leading to impaired mitochondrial function, insulin resistance, and steatohepatitis." (PMID 39161898, 2024). "We hope our study contributes to the efforts of finding new drug targets and agents for metabolic diseases, including type 2 diabetes, and recommends Sirt3 activators as potential agents in the treatment of insulin resistance and other metabolic abnormalities." (PMID 35409099, 2022). "We also reported that silencing of Sirt3 gene in APP/PS1 mice results in exacerbation of insulin resistance, neuroinflammation and β amyloid plaque deposition." (PMID 36396721, 2022). "We examined the brain samples of Sirt3-/- mice, fed on western diet and observed downregulation of metabolic enzymes, peripheral and central insulin resistance, mitochondrial dysfunction and inflammasome formation leading to neuroinflammation." (PMID 36396721, 2022). "We looked at the beneficial effects of SRT1720, a Sirt1 activator, Oroxylin-A, a Sirt3 activator, and their combination in insulin resistance/pre-diabetic rat heart." (PMID 33668369, 2021). "A significant decrease in fasting blood glucose levels and insulin resistance was observed after treatment with Sirt1 and Sirt3 activators." (PMID 33668369, 2021). "As Sirt1 and Sirt3 play an essential role in metabolic regulation, we were interested to evaluate the effect of Sirt1 and Sirt3 activation and their combination on fasting blood glucose levels and insulin resistance." (PMID 33668369, 2021). "In mice, SIRT3 plays a crucial role in maintaining the skeletal muscle insulin action, as well as in protecting against the effects of insulin resistance during HFD, through facilitation of glucose disposal and mitochondrial function." (PMID 33806509, 2021). "In the present study, we aimed to evaluate the effect of Sirt1, Sirt3 and combined activation in high fructose diet-induced insulin resistance rat heart and assessed the cardiac function focusing on mitochondrial health and function." (PMID 33668369, 2021). "Upregulation of SIRT1 in muscle cells protects against the effects of glucose-induced insulin resistance, through the reduction of mitochondrial dysfunction and oxidative stress, by increasing levels of SIRT3." (PMID 33806509, 2021).
Insulin resistance (continued). "All these findings indicate the potential role of SIRT3 in the function of β cells and its protective effect against high glucose/lipids/ROS environment of insulin resistance and type 2 diabetes." (PMID 32722262, 2020). "Increasing evidence has shown that SIRT3-deficinet mice displayed insulin resistance and glucose intolerance phenotypes upon feeding with the high-fat diet." (PMID 32722262, 2020). "A reduced SIRT3 content has been shown to increase insulin resistance and impair glucose oxidation by inhibition of PDH in favor of fatty acid utilization in skeletal muscle." (PMID 32612543, 2020). "These general parameters are like in previous reports, suggesting that diet-induced weight gain, insulin resistance and hypertriglyceridemia in Sirt3−/− mice, as an experimental model to study MetS." (PMID 30510203, 2018). "ALDH2 is likely to offer its protection by reversing insulin resistance-induced changes in mitochondrial integrity, Sirt3, and PGC-1α (pan/acetylated form)." (PMID 27634872, 2016). "Taken together, these findings revealed that ALDH2 protects against insulin resistance-induced cardiac defect likely through a Sirt3-dependent deacetylation of PGC-1α." (PMID 27634872, 2016). "Further study is warranted to unveil the mechanism behind ALDH2-mediated Sirt3 deacetylation in a more clinically relevant setting of insulin resistance-induced cardiomyopathy." (PMID 27634872, 2016). "The salient findings of our study indicated that ALDH2 exerts a protective effect against insulin resistance-induced cardiac contractile dysfunction through preservation of mitochondrial integrity and Sirt3 function." (PMID 27634872, 2016). "In conclusion, our data clarify and explain the Ang II intracellular molecular signaling that promotes insulin resistance in skeletal muscle cells through mitochondrial oxidative stress and Sirt3 dysfunction." (PMID 25993470, 2015). "believe that time-restricted fasting reduces insulin resistance by activating the SIRT3 pathway." (PMID 39925816, 2025). "Indeed, it has been shown that SIRT3 knock-out mice have higher levels of reactive oxygen species (ROS), leading to insulin resistance and type 2 diabetes." (PMID 39000044, 2024). "Moreover, insulin resistance is observed in Sirt3−/− mice as shown by the hyperglycemic-euglycemic clamp experiment." (PMID 36675125, 2023). "Conversely, the SIRT-3 inhibitor 3-TYP decreases insulin resistance." (PMID 36080416, 2022). "This suggests that insulin resistance might have a low level of Sirt3 expression and Sirt3 activator, and that HNK has beneficial effects on restoring dysregulation of proinflammatory cytokines in metabolic abnormalities." (PMID 35409099, 2022). "Finally, local insulin sensitivity is affected by expressions of SIRT1 and SIRT3, which reduce insulin resistance." (PMID 33806509, 2021). "Moreover, metformin ameliorates insulin resistance in muscle cells by upregulating glucose uptake through SIRT3." (PMID 33806509, 2021). "Finally, depletion of SIRT3 compromises the ability of adipose-derived mesenchymal stem cells to undergo adipogenic differentiation, and leads to adipocyte dysfunction and insulin resistance." (PMID 33806509, 2021). "After confirming the Sirt1 and Sirt3 activation on systemic and cardiac insulin resistance, we wanted to know the effect of Sirt1 and Sirt3 activation on lipid parameters i.e., triglycerides, LDL, HDL, serum free fatty acids and total cholesterol in pre-diabetic rats fed with high fructose diet." (PMID 33668369, 2021). "Furthermore, SIRT3 KO mice exhibited increased insulin resistance, which is underpinned by defective insulin-induced glucose uptake in skeletal muscle." (PMID 31130874, 2019). "In addition, HFD-fed Sirt3-KO mice exhibit increased insulin resistance due to defects in skeletal muscle glucose uptake." (PMID 30574122, 2018). "In contrast, overexpression of SIRT3 ameoliorated palmitate-induced endothelial insulin resistance." (PMID 27000941, 2016).
Insulin resistance (continued). "To further demonstrate the functional role of Sirt3 in the protective effect of ALCAR on Ang II-induced insulin resistance, we evaluated cell surface GLUT4 expression in Sirt3 siRNA and irrelevant siRNA-transfected L6 GLUT4-myc myotubes in the presence and absence of ALCAR." (PMID 25993470, 2015). "Here we found that 1) Ang II promotes insulin resistance through mitochondrial ROS, 2) enhanced mitochondrial O2• production leads to Sirt3 dysfunction, impairing mitochondrial antioxidant defense, 3) ALCAR protects against Ang II-induced insulin resistance by preventing Sirt3 dysfunction." (PMID 25993470, 2015). "Thus, while SIRT1 and SIRT6 positively regulate glucose uptake and fatty acid oxidation in skeletal muscle, SIRT1 activity is inhibited by SIRT4 and balanced by SIRT3, which inhibits fatty acid oxidation and affects ROS production, thereby influencing insulin resistance." (PMID 37006625, 2023). "The data suggest that Sirt3 activator might be a promising candidate for treatment of obese-induced insulin resistance and metabolic diseases, while Sirt3 inhibition might result in insulin resistance and other metabolic dysregulations." (PMID 35409099, 2022). "Thus, novel therapeutic approaches targeting SIRT3 activity may be important in providing new opportunities to treat insulin resistance and T2DM through maintaining mitochondrial health." (PMID 30972029, 2019). "Therefore, modulating SIRT3-mediated acetylation status could be a new and promising approach to prevent the onset of hyperinsulinemia and insulin resistance." (PMID 30683850, 2019). "Here in our study, mice with global or BAT regional endothelium-specific Sirt3 knockout exhibited BAT whitening and accelerated weight gain, as well as worsen glucose intolerance and insulin resistance." (PMID 40520025, 2025). "Sirtuins, including SIRT1, SIRT2, SIRT3, and SIRT6, play crucial roles in regulating cellular metabolism, and their dysregulation contributes to insulin resistance and diabetes, notably affecting skeletal muscle." (PMID 38904020, 2024). "A previous study demonstrated that RES treatment protected high-fat diet (HFD)-induced insulin resistance (IR) rats from diet-induced IR and elevated the expression of sirtuin 1 (SIRT1) and sirtuin 3 (SIRT3), mitochondrial DNA, and mitochondrial biogenesis." (PMID 38178962, 2023). "We observed significant exacerbation of peripheral and central insulin resistance and elevation of neuroinflammatory markers in APP/PS1/Sirt3-/- compared to APP/PS1 mice." (PMID 36396721, 2022). "Therefore, in this review, we focus on the mechanisms underlying SIRT3, SIRT4 and SIRT5-mediated regulation of mitochondrial function and metabolism, and also discuss the implication of their deficiency in the pathogenesis of insulin resistance and type 2 diabetes." (PMID 32722262, 2020). "Thus, considering the association between defective fatty acids β-oxidation, lipotoxicity and insulin resistance, targeting SIRT3 and mitochondrial protein acetylation may represent a promising approach in enhancing insulin sensitivity and improving metabolic health." (PMID 31130874, 2019). "Nevertheless, blunt of SIRT3 and SIRT1 in C2C12 cells impairs insulin pathway and stimulates insulin resistance." (PMID 30559718, 2018). "It's worth noting that SIRT1, SIRT2, SIRT3, and SIRT6 are positive regulators of insulin resistance in most cases." (PMID 30559718, 2018). "In vitro incubation of the ALDH2 activator Alda-1, the Sirt3 activator oroxylin A and the histone acetyltransferase inhibitor CPTH2 rescued insulin resistance-induced changes in aconitase activity and cardiomyocyte function (p < 0.05)." (PMID 27634872, 2016). "In this study, we provide evidence that by preventing the inhibitory effect of Ang II on Sirt3 expression and activity, ALCAR restored the antioxidant activity of MnSOD, rescuing skeletal muscle cells from mitochondrial superoxide-driven insulin resistance." (PMID 25993470, 2015).
Insulin resistance (continued). "In summary, AT-specific SIRT3 overexpression reverses HFD-induced insulin resistance independent of adiposity or energy intake." (PMID 40368890, 2025). "Moreover, Sirt3-EKO mice exhibited worsen glucose intolerance and insulin resistance, when compared with their littermate controls (Sirt3flox/flox mice, hereafter referred to as WT mice)." (PMID 40520025, 2025). "Similarly, NMN treatment can ameliorate insulin resistance induced via a high fat diet by restoring NAD+ biosynthesis and SIRT1/SIRT3 activity." (PMID 38256175, 2024). "Activation of Sirt3 by its activator, HNK, improves insulin sensitivity via enhancing lipolysis and glucose transport, which might be beneficial for treatment of insulin resistance or type 2 diabetes." (PMID 35409099, 2022). "Likewise, NMN treatment ameliorates HFD-induced insulin resistance by restoring NAD+ biosynthesis and SIRT1/SIRT3 activity." (PMID 35563288, 2022). "However, further investigation into the targets and functions of SIRT1, SIRT2, SIRT3, and SIRT6 will aid in the development of new strategies to treat insulin resistance and T2DM." (PMID 30972029, 2019). "Furthermore, the possible involvement of Sirt3-mediated deacetylation of PGC-1α, in insulin resistance- and ALDH2-induced cardiac contractile and mitochondrial responses was substantiated by the pharmacological manipulation of Sirt3 acetylation and HAT." (PMID 27634872, 2016). "The Sirt3 activator Oroxylin A and the histone acetyltransferase inhibitor CPTH2 obliterated (p < 0.05 vs. high insulin group) or overtly dampened insulin resistance-induced cardiomyocyte dysfunction and mitochondrial injury (aconitase activity) without eliciting any effects themselves." (PMID 27634872, 2016). "Nevertheless, since the hepatic PGC-1α pathway is induced in models of insulin resistance and stimulates glucose production, repression of the PGC-1α-ERRα pathway is likely to play a significant role in reduction of SIRT3 expression by metformin in the diabetic liver." (PMID 23166782, 2012). "Although Sirt1 and Sirt3 activation able to reduce insulin resistance, we could not observe any additional benefit with the combination." (PMID 33668369, 2021). "The likely mechanism of WBC influence on increasing the concentration of Sirt3, as we have shown in older training men, may be the effect of repeated WBC treatments on lowering glucose and insulin resistance, as demonstrated in previous studies among patients with hyperglycaemia." (PMID 33396247, 2020). "Thus, Sirt3 could be the unifying intracellular molecular signaling through which L-carnitine and its esters, including ALCAR, protect mitochondria and ameliorate insulin resistance." (PMID 25993470, 2015). "Mice lacking SIRT3 and fed a high-fat diet (HFD) displayed accelerated metabolic syndromes including obesity, insulin resistance, and hepatic steatosis when compared to wild-type mice." (PMID 39000044, 2024).
Hypertension (65 papers, 2011 to 2026). The presence of chronic increased pressure in the systemic arterial system. "SIRT3-mediated deacetylation is essential for guaranteeing the activity of SOD2 to protect against vascular oxidative stress, and SIRT3 deficiency increased the production of mitochondrial superoxide free radicals and promoted the occurrence of hypertension." (PMID 40421455, 2025). "Particularly, clinical studies demonstrated that risk factors of cardiovascular diseases were associated with decreased SIRT3, and overexpressing SIRT3 reduced hypertension in animal models." (PMID 39000044, 2024). "Dikalova demonstrated that SIRT3 deficiency increased vascular dysfunction by enhancing inflammation and oxidative stress in hypertension." (PMID 39300372, 2024). "In Sirt3‐deficient mice, Sirt3 depletion was associated with hypertension and hyperacetylation of MnSOD, conducting to the loss of MnSOD activity and to mitochondrial oxidative stress, that were accompanied with vascular damage and early vascular senescence." (PMID 38924381, 2024). "Subsequent investigations revealed that SIRT3 expression was reduced in the renal tissues of aged TG mice expressing the Hap-I variant, implicating SIRT3 in the renal damage associated with hypertension." (PMID 39911234, 2024). "The mitochondrial deacetylase Sirt3 has been implicated in the amelioration of vascular dysfunction and hypertension by attenuating vascular inflammation and oxidative stress." (PMID 39046654, 2024). "Hypertension is intricately linked to the reduction and inactivation of the crucial mitochondrial enzyme, sirtuin-3." (PMID 37955687, 2023). "Loss of SIRT3 promotes endothelial dysfunction, oxidative stress, and vascular hypertrophy in essential hypertension, leading to cardiac dysfunction." (PMID 35855865, 2022). "Changes in the function of SIRT1 and SIRT3 significantly affect the vascular function associated with hypertension." (PMID 34331512, 2021). "In this study, using NG2-DsRed mice to trace pericytes, we aimed to investigate the mechanism of hypertension-induced renal fibrosis involving SIRT3-associated pericyte pathway." (PMID 33233553, 2020). "The RSV/QSC treatment increased SIRT1 and SIRT3 expression independently from their role in the regulation of some the mechanisms that underlie hypertension studied in this paper." (PMID 32210194, 2020). "When rats were fed high-salt diets, it was shown that hypertension may cause atrial fibrillation (AF) and alteration of lipid metabolism; AF sensitivity was increased when the SIRT3/AMPK signaling pathway was inhibited (Wang X.-H." (PMID 41567643, 2025). "SIRT3 is also protective against hypertension, a prominent risk factor for coronary artery disease." (PMID 33499277, 2021). "However, less information is available about the association between SIRT3 and endothelial autophagy in hypertension." (PMID 32015327, 2020). "On the other hand, SIRT3 transgenic endothelial-specific mice (TgEC) exhibited alleviation of Ang II-induced renal fibrosis, EndoMT, and oxidative stress, indicating that SIRT3 plays a protective role in mitigating hypertension-induced kidney damage." (PMID 40218970, 2025). "Sirt3 depletion in hypertension leads to endothelial dysfunction, vascular hypertrophy, inflammation, and end-organ damage." (PMID 40404619, 2025). "Collectively, these findings indicate that RSV mitigates mitochondrial oxidative stress, apoptosis, and ferroptosis through activation of the AMPK/Sirt3 pathway, contributing to the suppression of hypertension development in SIH rats." (PMID 40074082, 2025). "Contrarily, mice globally overexpressing Sirt3 (Sirt3OX) were protected from Ang II‐induced vascular oxidative stress and damage, and showed an alleviation of hypertension." (PMID 38924381, 2024). "The loss of SIRT3 leads to increased SOD2 acetylation, causing severe oxidative stress, hypertension, and endothelial dysfunction." (PMID 39458930, 2024).